IL6 (interleukin 6)
Diseases named in the same sentence as IL6 in open-access papers (continued):
Sharing a sentence is not in itself a finding about the gene and the disease.
cancer (continued). "It has also been shown that the high concentration of TNFα found in these patients correlates strongly with increased advancement of the cancer, a shortened survival period, and increased expression of IL-6." (PMID 36834426, 2023). "In recent years, research has shown that interleukin 6 (IL6) induces EMT of cancer cells by STAT3 activation." (PMID 37651362, 2023). "Conglomeration of all our observations has suggested that MDSC secreted IL-6/IL-10/IL-1β are the supreme players regulating the drug resistance of cancer cells via STAT1/STAT3/NF-κB pathway." (PMID 38304256, 2023). "LIF and LIFR, members of the interleukin-6 (IL-6) cytokine family, constitute a poorly-defined pathway connecting inflammation to cancer." (PMID 36925915, 2023). "Positive correlations between YKL-40 and other biomarkers involved in cancer-promotion or systemic inflammation (IL-6, IL-8, and CRP) were identified in this study." (PMID 37744345, 2023). "Overall, altered IFN, including both IFN-α and IFN-γ responses, IL-6, and IL-7 signaling pathways have been noted in cancer patients’ peripheral immune cells compared to those of healthy donors." (PMID 37741983, 2023). "Many studies indicate that interleukin-6 (IL-6) accelerates cancer cells survival and proliferation through the phosphorylation of a cell-signaling protein, STAT3." (PMID 37191432, 2023). "To better understand the connections among differentially expressed genes in the Cancer Hallmark pathway analysis, we performed KDDN analysis to identify novel connections induced by SI or JGT in the IL6/JAK/STAT3 and OXPHOS pathways." (PMID 36980301, 2023). "Under hypoxic conditions, interleukin-6(IL-6) produced by cancer cells induces the activation of Schwann cells and triggers the development of PNI, which is also accompanied by the activation of a series of hypoxia-associated signaling pathways." (PMID 36900158, 2023). "Various studies have reported that cytokines, including IL-6, are expressed in cancer cells themselves." (PMID 37880751, 2023). "EMT-inducing factors such as TGFβ1 and IL6 were upregulated in H69 following direct interaction (cluster 1), suggesting that multiple concomitant pathways are activated in cancer cells in our system." (PMID 36936987, 2023). "After reviewing a total of 73 articles across both cancer types and based on our selection criteria, IL-6 was the most prevalent biomarker identified." (PMID 37181043, 2023). "This inflammatory state is frequently observed in cancer settings, particularly at the initiation of radiotherapy, triggering an overproduction of inflammatory cytokines such as interleukin-1, interleukin-6, and tumor necrosis factor-alpha." (PMID 37732299, 2023). "Further analysis of genes dysregulated in cancer associated neutrophils revealed that TNF-α, Oncostatin M (OSM), IL-1β and IL-6 cytokines are expressed in the neutrophils with corresponding expression of their receptors in CTCs." (PMID 37006265, 2023). "DCs in the TME are often dysfunctional due to cancer cell secreted factors (e.g., IL-6, VEGF, TGF-β, and reactive oxygen species (ROSs))." (PMID 37190281, 2023). "Hepatic macrophages are the primary cells responsible for the production of “cancer-promoting cytokines,” such as IL-6 and TNF-α, in response to LPS." (PMID 37896221, 2023). "Significant decrease in TNF-α and IL-6 in serum, beneficial effects on cancer-related fatigue and quality of life compared to placebo." (PMID 36969071, 2023). "In cancer, IL-6 induces natural killer (NK) cell proliferation which contributes to the MHC-nonrestricted cytotoxic activity of those cells." (PMID 37588093, 2023). "More importantly, NK-LAAO-produced IL-6 enables cancer cells to gain the EMT phenotype and metastatic potentials." (PMID 37385076, 2023). "Cancer-derived EVs trigger the release of IL-6, a pro-inflammatory cytokine, by bone-marrow derived macrophages by activating the IL-6-STAT3 signaling cascade." (PMID 37025182, 2023).
cancer (continued). "We indicated that the Fc-VFD inhibits the secretion of proangiogenic factor, VEGF-A and IL-6, from cancer cells, endothelial cells, and macrophages in the TME." (PMID 35895109, 2023). "A few trials evaluated the efficacy of IL6 inhibitors in cancer patients, but so far, the results have been unsatisfactory." (PMID 37958474, 2023). "The anti‐cancer activity of PPIs is based on the fact that it can significantly reduce the production of acid‐active substances, IL‐6 and nitric oxide, especially TNF‐α, expression of inducible NOS and COX‐2." (PMID 35961680, 2023). "Elevated levels of all three markers were associated with risk of cancer within 3 months: CRP (odds ratio (OR) 4.41, 95% confidence interval (CI) 2.86–6.81), IL‐6 (OR = 2.89, 1.91–4.37) and YKL‐40 (OR = 2.42, 1.59–3.66)." (PMID 36440611, 2023). "Numerous experimental and clinical studies proved the pathological functions of IL-6 in autoimmunity, inflammation and cancer." (PMID 37189804, 2023). "Previous studies have shown that CAFs promote carcinoma progression by inducing EMT via the IL-6/JAK2/STAT3 pathway or paracrine TGF-β." (PMID 37254126, 2023). "Different cytokine-related pathways were upregulated in the stroma during the progression from normal mucosa to carcinoma, including interferon γ, interleukin (IL)-11, IL-10, IL-6, IL-9, IL1R and IL-18 signalling pathways." (PMID 36442992, 2023). "More importantly, fibroblasts incubated with EVs derived from RCC cells showed a higher level of IL-6, which has an important role in promoting carcinoma metastasis." (PMID 37481520, 2023). "Similar to gp130, vesicular Anx II coupling with STAT3 stimulates other signaling pathways in M2 polarization including the p38MAPK, and NF-κB pathways in macrophages, leading to augmented IL-6 and cancer progression." (PMID 36612080, 2022). "IL-6 is a proinflammatory cytokine secreted by cancer cells, cancer stromal cells, and adipocytes as well as immune cells." (PMID 36233285, 2022). "So, decay in macrophages would lead to less secretion of IL-6, leaving cancer cells with fewer resources and vice versa." (PMID 36294824, 2022). "LIF, a pleiotropic cytokine of the interleukin 6 families, participates in numerous vital biological processes, including cell differentiation, cancer metastasis, relapse, and drug resistance." (PMID 35654787, 2022). "At this time, SOCS3 enters into action and, to prevent over-invasion of cancer cells, in cooperation with Interleukin 6, provides conditions for strengthening the immune system and inflammatory responses." (PMID 35928368, 2022). "Cytokine activation of STAT3 is considered the principal pathway in the activation of cancer, and IL-6 is considered an upstream activator of JAK2/STAT3." (PMID 36313702, 2022). "Previous studies reported that two small soluble members of CXC chemokine family, IL-6 and IL-8, are critical to the development of cancer cells." (PMID 35053925, 2022). "Earlier studies have reported that FK866 is a NAMPT inhibitor and controls cancer progression by a downregulation of TNFα, IL-6 expressions, CXCR4." (PMID 36497496, 2022). "IL-6 plasma levels have been directly associated with the pathogenesis of CCS and increased mortality in cancer patients." (PMID 35743911, 2022). "IL-6 overexpression in cancer tissues promotes the growth and development of tumors by increasing the inflammatory response around the tissues in the tumors." (PMID 35392643, 2022). "LIFR and its major ligand LIF belong to the interleukin-6 (IL-6) cytokine family and have a central role in immune system regulation, carcinogenesis, and dissemination in several human cancers." (PMID 35847866, 2022). "We demonstrated that cancer-derived interleukin-6 (IL-6) stimulates STAT3-dependent, nuclear factor-κB-mediated indoleamine 2,3-dioxygenase (IDO) upregulation in eMDSCs which triggers immunosuppressive effects of eMDSCs." (PMID 36329699, 2022).
cancer (continued). "Because osteopontin (OPN), IL‐1β, tumor necrosis factor (TNF)‐α, and IL‐6 are well‐known growth factors derived from macrophages, cancer cells were stimulated with these recombinant proteins, and cell proliferation was assessed with the WST assay." (PMID 35132816, 2022). "IL-6 is highly expressed in the serum and cancer tissues of GC patients and is related to the depth of cancer invasion and degree of differentiation." (PMID 36185234, 2022). "IL-6 administration also temporarily increased leptin levels in cancer patients in a dose-dependent manner." (PMID 36558477, 2022). "This was further supported by evidence that, even when autophagy was inhibited, IL-6 administration led to cancer stem-cell maintenance." (PMID 36295867, 2022). "This is in accordance with a report showing a decline in IL-6 levels in cancer patients treated with the anti-PD-L1 antibody Atezolizumab." (PMID 35444660, 2022). "The results indicated that CnP suppresses the expression of α-SMA and collagen I synthesis in CAFs and hampers the cancer–stromal crosstalk by decreasing the secretion of IL-6, IL-8, CCL2, and CXCL12." (PMID 35327514, 2022). "In early CRC, production of both IL-8 and IL-6 by myofibroblasts in the TME is responsible for cancer stem cells expansion and maintenance through the regulation of Notch-STAT3 pathways." (PMID 36289899, 2022). "Application of the IL‐6 inhibitor tocilizumab can be a choice for modulation of steroid‐refractory irAEs occurring secondary to the ICI therapy in cancer patients." (PMID 35301813, 2022). "In other words, the plant extract caused a significant change in the IL-6 levels and STAT3 expression in HepG2 hepar cancer cells." (PMID 37829248, 2022). "Neither the guidelines nor the ASCO education book discuss the role of inflammation and cytokines, such as IL-1β, IL-6, JAK/STAT pathway, or IFN-γ, all of which have been associated with cancer cachexia." (PMID 36358681, 2022). "Mechanistic studies suggest a complex role of IL-6 in cancer development, with effects at both local and systemic levels, mainly mediated through the JAK/STAT3 signaling pathways." (PMID 35948877, 2022). "In cancer cells, abnormal IL-6 expression and constitutive hyperactivation of STAT3 are closely correlated with an enhanced cancer cell proliferation and drug resistance." (PMID 35813468, 2022). "Up-regulation of autophagy in CAFs promotes the secretion of IL-6 and IL-8, whereas autophagy inhibition significantly suppresses release of these cytokines as well as cancer progression." (PMID 35927755, 2022). "Further, our immunoblotting and immunoflurescence data showed that CSC specific transcription factors, Sox-2, Oct 3/4 and Nanog were enhanced in cancer cells upon treatment with IL-6." (PMID 35300689, 2022). "Chronic inflammation promotes cancer progression by increasing the production of pro-tumorigenic cytokines, mainly IL-6, IL-17A, IL-22 and IL-23, which activate NF-κB and STAT3 signaling pathways." (PMID 35387985, 2022). "In contrast, IL-6 is a cytokine well known to be involved in the development and progression of many cancer types, including CRC." (PMID 36362062, 2022). "For instance, the inhibition of cancer cells by cytotoxic T-cells, IFN-γ, or natural decay, and its promotion by IL6 and natural growth, are direct pathways that increase or decrease the number of cancer cells." (PMID 36294824, 2022). "In particular, a large body of evidence supports the connection between IL-6 and cancer development." (PMID 36289746, 2022). "SNHG12 recruits NF-κB to the IL-6R promoter, increasing IL-6R expression and promoting IL-6/miR-21 interaction between cancer cells and M2 macrophages, enhancing PD-L1 expression." (PMID 36612180, 2022). "Some cachexia-inducing factors such as IL-6 were shown to be upregulated in preclinical cancer cachexia models, although none are widely increased in cachectic patients with different cancers." (PMID 36428623, 2022).
cancer (continued). "Compared with the human normal glial cell line (HEB), PLCG1, IL18, and IL6 were highly expressed in cancer cell lines (U251 and U87)." (PMID 36605437, 2022). "In the context of cancer and chronic inflammatory diseases, IL-6 has been shown to induce the production of MMPs from macrophages." (PMID 35512020, 2022). "Subsequent studies by us confirmed concentrations of IL-6 in the range of 1–5 μg/mL in sera of cancer patients subjected to immunotherapy; such sera contained IL-6 in high molecular mass complexes as judged by Sephadex G-200 gel filtration." (PMID 35406728, 2022). "The inhibitor related to the blockage of IL-6 and IL-6R such as tocilizumab is considered as an effective anti-cancer therapeutic approach." (PMID 36091805, 2022). "Extracellular vesicles and cancer-cell-derived exosomes can interact with inflammatory cytokines (IL-6 and IL-8) to promote the formation of PMN." (PMID 36289773, 2022). "Our results suggested that Lon-induced Ca2+-dependent cisplatin resistance is involved in chemotherapy-induced cancer stemness, which is consistent with the reported roles of PYK2, SRC, and STAT3/IL-6 in the enrichment of cancer stem cells." (PMID 35296653, 2022). "This is in line with much general information that supports that the natural immune system functional status, in particular IL-6 levels, is related to general survival in cancer patients." (PMID 36289746, 2022). "IL‐6 was the only cytokine expressed in higher concentrations in cachectic participants compared with non‐cachectic cancer patients." (PMID 35080147, 2022). "LDOC1 deficiency leads to enhanced IL-6/JAK2/STAT3 loop, through which LDOC1 mediates cancer progression." (PMID 36591515, 2022). "It is interesting that systemic IL-6 levels were inversely correlated with endometrial CD3+ T cells since the cancer-promoting properties of IL-6 are well known." (PMID 34857870, 2022). "IL-6 is also one of the major cytokines in cancer and plays a key role in cancer progression, metastasis, and therapeutic resistance." (PMID 35804048, 2022). "Cisplatin has been shown to increase IL-6 release and TGF-β expression in cancer-associated fibroblasts." (PMID 36313710, 2022). "We have previously reported that Rab37 small GTPase mediates secretion of IL-6 in macrophages to promote cancer progression, whereas the roles of Rab37 in the intracellular trafficking and exocytosis of CHI3L1 are unclear." (PMID 34987649, 2022). "Saliva cytokine levels of IL-1β, IL-2, IL-6 and TNF are not only associated with oral inflammation but also with the severity of oral mucosal damage in cancer patients." (PMID 35844493, 2022). "The chemokines and cytokines produced by cancer cells (mainly IL-6, IL-10 and TGF-β), have a huge systemic impact." (PMID 35741450, 2022). "Marked increase in IL-6 and IL-10 levels subsequent to PTX administration in cancer patients have been reported to be associated with joint pain and fatigue." (PMID 35273508, 2022). "Cancer-induced inflammation inhibits hematopoiesis by the interaction of interleukin 6 and tumor necrosis factor-alpha (TNF-α)." (PMID 36364711, 2022). "To explore the role of TAMs derived IL-6 in inducing metastasis in cancer cells, we performed transwell migration assay." (PMID 35300689, 2022). "The levels of G-CSF and IL-6 were analyzed by HIC assay, which demonstrated IL-6 and G-CSF intratumoral and peritumoral expression both in cancer cells and in macrophages." (PMID 36010260, 2022). "IL-6 is an inducer of STAT3, and is a direct target of miRNA-26a and -26b, and STAT3 signaling is associated with cancer progression and metastasis." (PMID 36138741, 2022). "Some inflammatory cytokine signature predicted the effectiveness of the anti-cancer medication, for example, IL-6 level is a prognostic marker for survival in advanced NSCLC patients or those treated with chemotherapy." (PMID 36005200, 2022).
cancer (continued). "The CD10 and GPR77 double-positive CAF subset secretes IL-6 and IL-8, sustaining cancer stemness and promoting chemoresistance." (PMID 36424598, 2022). "But λCA, λCIL6 and λA, specify that controlling the processes for which cancer production is promoted by IL6 and adipocytes or even reducing the production of these two can lead to a better result." (PMID 35294447, 2022). "If cancer cells can be controlled with chemotherapy, then IL-6 production is assumed to be relatively suppressed, resulting in the persistence of a chronic mild inflammatory state." (PMID 35949598, 2022). "Among cytokines correlated with inflammation-induced oncogenesis, IL-6 predominantly regulates all cancer hallmarks and can be present in different stages of cancer development from promotion to metastasis." (PMID 36298472, 2022). "IL-6 is a multifunctional cytokine with various roles in immunity, development, metabolism, aging, and cancer and can stimulate B cells to produce antibodies." (PMID 36118092, 2022). "In this review, we will discuss inflammaging in the elderly, specifically concentrating on IL-6 and IL-1β in the context of T lymphocytes, and how inflammation is related to mortality and morbidities, specifically cardiovascular disease and cancer." (PMID 35821823, 2022). "Administration of an antibody against IL-6R or genetic ablation of IL-6 significantly improved survival while reducing muscle wasting, whereas treatment with exogenous IL-6 resulted in muscle wasting in cancer-free mice." (PMID 35328423, 2022). "Dormancy has been described as a common feature of cancer cells derived from a hypoxic microenvironment, and IL-6 expression has been reported to be related to a dormant phenotype." (PMID 36497411, 2022). "SMG1 upregulation by IL-6/STAT3 is exacerbated in the context of cancer immunotherapy as there are higher levels of IL-6 hampering the efficacy of the treatment." (PMID 36443756, 2022). "Monoclonal antibodies can target immune checkpoints (e.g., PD-L1 and CTLA-4), tyrosine kinase and subsequent signaling pathways (e.g., VEGF), and cytokines in cancer patients (e.g. IL-6 and IL-1β)." (PMID 35054524, 2022). "In this review, we summarise the role of IL-6 signalling pathways in cancer biology, with particular emphasis on cancer cell invasiveness and metastasis formation." (PMID 36429126, 2022). "Specifically, IL-6, whose anticarcinogenic properties have been already discussed, increases acutely after an exercise bout in both healthy subjects and cancer patients." (PMID 35454797, 2022). "Various cytokines, such as TNF-α, TGF-β, IL-10, and especially IL-1β and IL-6, are well studied and have been shown to be involved in the complex crosstalk between cancer initiation/progression and sleep–wake cycles." (PMID 35246220, 2022). "Adipocytes and IL6 play crucial roles in the cancer dynamics given their roles and the similarity between cancer dynamics and their dynamics." (PMID 35294447, 2022). "Various reports have demonstrated that IL-6 regulates its various functions in different types of cancer primarily through JAK/STAT pathway." (PMID 35300689, 2022). "In the cancer context, it is known that the IL-6 is responsible to promote tissue invasion, EMT, acute-phase proteins and Th17 cells." (PMID 35626741, 2022). "A large part of their actions is based on their high secretory activity, leading to the exposure of cancer cells to all kinds of bioactive factors, such as interleukin-6 (IL-6)." (PMID 36291767, 2022). "The systemic inflammatory response of cancer prompts neutrophil infiltration, resulting in the secretion of interleukin-2 (IL-2), interleukin-6 (IL-6), interleukin-10 (IL-10), tumor necrosis factor α (TNF-α), and vascular endothelial growth factor (VEGF)." (PMID 35407463, 2022).